SERPINB3 (serpin family B member 3)
Diseases named in the same sentence as SERPINB3 in open-access papers (continued):
Sharing a sentence is not in itself a finding about the gene and the disease.
cervical tumor (4 papers, 2020 to 2024). "We recently demonstrated that SERPINB3 also protects cervical tumor cells against RT-induced cell death by preventing lysoptosis." (PMID 37279067, 2023). "This is consistent with our prior study showing that human cervical tumor cell lines expressing SERPINB3 are more radioresistant than control tumors in an athymic nude murine model." (PMID 37279067, 2023). "Guided by expression patterns in primary cervix tumor samples, we identified cathepsin L as at least one of the cysteine protease targets of SERPINB3 in cervical tumor cells that mediates radiation-induced cell death in the absence of SERPINB3." (PMID 35022555, 2022). "Transcriptomics analysis of primary cervix tumor samples and genetic knock out demonstrates a role for the lysosomal protease cathepsin L in radiation-induced cell death in SERPINB3 knock-out cells." (PMID 35022555, 2022). "Rescue with wild-type SERPINB3 or a reactive site loop mutant indicates that protease inhibitory activity is required to protect cervical tumor cells from radiation-induced death." (PMID 35022555, 2022). "Therefore, we hypothesized that CTSL was the most-likely target of SERPINB3 in cervix tumor cells and generated stable knockout cell lines using CRISPR-Cas9 targeting of CTSL in the SW756-B3-WT and –B3-KO backgrounds." (PMID 35022555, 2022). "Additionally, the SERPINB3 RSL is required for protection against radiation, and knockout of the lysosomal cysteine protease cathepsin L (CTSL) partially protected SERPINB3-KO cervix tumor cells from radiation-induced death, further supporting the mechanism of lysosomal protease inhibition." (PMID 35022555, 2022). "Given the conserved molecular function of SERPINB3 as an intracellular lysosomal cysteine protease inhibitor, we hypothesized that cervical tumor cells lacking SERPINB3 would be susceptible to lysosomal membrane permeability and lysosomal rupture following an insult such as ionizing radiation." (PMID 35022555, 2022).
cholangiocarcinoma (4 papers, 2022 to 2024). A carcinoma that arises from the intrahepatic biliary tree (intrahepatic cholangiocarcinoma) or from the junction, or adjacent to the junction, of the right and left hepatic ducts (hilar cholangiocarcinoma). "Cholangiocarcinoma is characterized by a very poor outcome and SerpinB3, a serine protease inhibitor, has recently been found to play a relevant role in malignant transformation in different cancers." (PMID 38201652, 2024).
Epithelial Ovarian Cancer (4 papers, 2010 to 2025). "To compare the expression patterns of SERPINB3 protein between chicken and human ovarian cancer cells, we conducted immunofluorescence analysis." (PMID 23185467, 2012). "SERPINB3 protein was rarely detected in normal cells, but abundant in the nucleus of ovarian cancer cells of laying hens." (PMID 23185467, 2012). "Nevertheless, dysfunctional permeabilization of lysosomes contributes to the development of chemoresistance in ovarian cancer cells, and SERPINB3 confers resistance to drug-induced apoptosis by inhibiting lysosomal cathepsin proteases in cancer cells." (PMID 23185467, 2012). "Similarly, SERPINB3 protein was abundant in the nucleus of three human ovarian cancer cell lines, OVCAR-3, SKOV-3 and PA-1 cells." (PMID 23185467, 2012). "SERPINB3 protein was localized predominantly to the glandular epithelium in cancerous ovaries of chickens, and it was abundant in the nucleus of both chicken and human ovarian cancer cell lines." (PMID 23185467, 2012). "However, there is little known about the SERPINB3 expression in human epithelial ovarian cancer (EOC)." (PMID 23185467, 2012). "Moreover, we recently reported that SERPINB3 is a biomarker for chicken ovarian endometrioid carcinoma and that it can serve as a prognostic factor for platinum resistance and poor survival in patients with epithelial ovarian cancer." (PMID 22496782, 2012).
esophageal tumors (4 papers, 2017 to 2025). "Similarly, genome-level and IHC analyses showed upregulated PD-L1 in SERPINB3-high ovarian and esophageal tumors." (PMID 37279067, 2023).
allergic disease (3 papers, 2021 to 2022). An immune response that occurs following re-exposure to an innocuous antigen, and that requires the presence of existing antibodies against that antigen. "SERPINB3 and SERPINB4 in patients suffering from allergic disease control the viability of Th2 cells by exerting anti-apoptotic effects." (PMID 34126986, 2021). "Expression of several members in clade B, such as SERPINB2, SERPINB3 and SERPINB4, is upregulated in allergic diseases, and they modulate Th1/Th2 responses." (PMID 34126986, 2021). "SERPINB3 and SERPINB4 are upregulated in memory Th2 and innate helper 2 cells of allergy patients." (PMID 35626221, 2022).
colon carcinoma (3 papers, 2015 to 2021). "In preliminary experiments we have analyzed SerpinB3 expression in different human colon carcinoma cell lines (RKO-E6, SW48, HCT 116, HT29 and HTC 15)." (PMID 28178650, 2017).
colorectal cancer (3 papers, 2017 to 2024). A primary or metastatic malignant neoplasm that affects the colon or rectum. "In conclusion, in patients with colorectal cancer the expression of SerpinB3 was higher in more advanced tumor stages and it was correlated with histological parameters of poor prognosis." (PMID 28178650, 2017). "We evaluated colorectal cancer specimens from 105 patients and a positive correlation between SerpinB3, COX-2 and β-Catenin expression was observed, with higher levels in tumor than in adjacent tissue." (PMID 28178650, 2017). "In conclusion, in colorectal cancer SerpinB3, COX-2 and β-Catenin are positively correlated and associated with more advanced tumor stage." (PMID 28178650, 2017). "In colorectal cancer, SerpinB3, COX-2 and β-catenin have been found to be associated with more advanced tumor stages, and in vitro experiments have also shown that SerpinB3 determines the upregulation of COX-2/ β-catenin positive loops, which is associated with invasive histologic features." (PMID 38201652, 2024). "Aim of the present study was to clarify the relationship between SerpinB3, COX-2 and β-Catenin in colorectal cancer analyzing tumor samples of well characterized patients and cell lines with different expression of SerpinB3." (PMID 28178650, 2017).
hepatoblastoma (3 papers, 2015 to 2024). Hepatoblastoma (HB) is a malignant hepatic tumor and is the most common pediatric liver cancer. "A previous study from our group has shown that SerpinB3 is expressed in the majority of hepatoblastomas, where SerpinB3 levels were positively correlated with the extent of Myc expression and tumour diffusion." (PMID 26634820, 2015). "In addition, this serpin was found highly expressed in hepatoblastomas, a tumor originating from liver embryonic cells and once again SerpinB3 levels were positively correlated with Myc expression." (PMID 26634820, 2015). "Concurrently, the serine/cysteine protease inhibitor SERPINB3, which is directly manipulated by SERPINB4, is modulated by hypoxia through the hypoxia-inducible factor-2α (HIF-2α), and has been recently proven to be upregulated in human hepatoblastoma." (PMID 34069906, 2021).
inflammatory skin disease (3 papers, 2015 to 2025). Inflammatory skin disorders covers a broad category that includes many conditions ranging in severity, from mild itching to grave medical health complications These disorders are common in people of all ages and races. "Finally, identifying therapeutic targets within the SERPINB3/4 pathway holds promise for developing novel and effective treatments for PN and related inflammatory skin disorders." (PMID 40995892, 2025).
liver fibrosis (3 papers, 2017 to 2024). "The serine protease inhibitor SerpinB3 has been described as critical mediator of liver fibrosis and it has been recently proposed as an additional hepatokine involved in NASH development and insulin resistance." (PMID 38307387, 2024). "In the present study we analyzed the pro-fibrogenic action of SerpinB3 in cell cultures and in two different murine models of liver fibrosis." (PMID 28611447, 2017). "For evaluating the actual impact of SerpinB3 on the evolution of hepatic fibrosis TG-SB3 mice and corresponding WT littermates were exposed to chronic liver injury." (PMID 28611447, 2017). "SerpinB3 up-regulation in CLD patients has been reported to correlate with the extent of liver fibrosis and the production of transforming growth factor-β1, but the actual role of SerpinB3 in hepatic fibrogenesis is still poorly characterized." (PMID 28611447, 2017). "In both experimental models, SerpinB3 overexpression significantly worsened liver fibrosis and this was related to a net increase in the transcript levels of pro-fibrogenic genes, as well as of collagen deposition and the number of αSMA-positive HSC/MFs as compared to wild-type mice." (PMID 34359934, 2021). "The profibrogenic action of SerpinB3 has been outlined using transgenic mice manipulated to overexpress SerpinB3 in hepatocytes and submitted to two distinct protocols for induction of liver fibrosis, namely, chronic CCl4 treatment and the NASH-related MCD diet." (PMID 34359934, 2021).
metabolic dysfunction-associated steatotic liver disease (3 papers, 2022 to 2024). Metabolic dysfunction-associated steatotic liver disease (MASLD, formerly known as nonalcoholic fatty liver disease or NAFLD) is a type of liver disease that is not caused by alcohol. "The pro-fibrogenic role of SerpinB3 was also investigated both in vitro and in animal models of metabolic dysfunction-associated steatotic liver disease (MASLD) and metabolic dysfunction-associated steatohepatitis (MASH)." (PMID 39061218, 2024).
pancreatic cancer (3 papers, 2023 to 2024). "Although SERPINB3 has been implicated in proinflammatory signaling in pancreatic cancer and Kras-mutant tumors, the underlying molecular mechanism is unknown." (PMID 37279067, 2023). "A recent study has also shown that the SerpinB3–Myc axis is upregulated in the basal-like/squamous subtype of pancreatic cancer, known for its aggressiveness." (PMID 38201652, 2024).
systemic lupus erythematosus (3 papers, 2018 to 2024). An autoimmune multi-organ disease typically associated with vasculopathy and autoantibody production. "Dysregulated apoptosis as a result of aberrant SERPINB3 expression has been shown to be implicated in autoimmune diseases such as systemic lupus erythematosus because the inefficient disposal of apoptotic debris results in the rescue of autoreactive immune cells." (PMID 36833193, 2023). "Moreover, exogenous administration of SERPINB3 to lupus-prone mice causes increased concentrations of SERPINB3 in mice sera and tissues, therefore one may claim that it does not mirror the physiological activity of SERPINB3." (PMID 30254646, 2018). "In summary, our data have shown that exogenous SERPINB3 induces a remarkable improvement in terms of both survival and clinical outcome in lupus-prone mice." (PMID 30254646, 2018). "The involvement of SerpinB3 in immune modulation was also studied in a murine model of systemic lupus erythematosus, in which the administration of SerpinB3 resulted in increased levels of Tregs in the spleen, leading to a more tolerant immune phenotype and slower disease progression." (PMID 39061218, 2024). "SERPINB3 was shown to be expressed on CD27+ B lymphocyte surface of healthy donors, while it was absent on CD27+ cells of lupus patients." (PMID 30254646, 2018).
allergic rhinitis (2 papers, 2021 to 2025). Inflammation of the nasal mucous membranes caused by an IgE-mediated response to external allergens. "The proteins ORM, APOH, FGA, CTSD, and SERPINB3, which showed promise in preclinical studies for predicting response to glucocorticoids, have also been evaluated in clinical trials involving patients with seasonal allergic rhinitis (SAR)." (PMID 40551926, 2025).
autoimmune disease (2 papers, 2023). A disorder resulting from loss of function or tissue destruction of an organ or multiple organs, arising from humoral or cellular immune responses of the individual to their own tissue constituents. "The next question is what did the SERPINB3 mutations do to predispose the patients to the autoimmune disease AOID with the production of IFN-γ autoantibodies and pustular reaction." (PMID 36833193, 2023). "In addition, elevated SERPINB3 expression is also found in autoimmune disorders and implicated in the induction of inflammatory cytokines." (PMID 37279067, 2023). "However, in both tumors and autoimmune diseases, the mechanistic link between SERPINB3 and immune regulation remains poorly understood." (PMID 37279067, 2023).
autoimmune disorder (2 papers, 2015 to 2023). "Although the precise physiological functions of SERPINB3 are elusive, it has been hypothesized that SERPINB3 might be involved in the development of autoimmunity." (PMID 25991924, 2015).
breast tumors (2 papers, 2023 to 2025). "To assess whether the TNBC-enriched epithelial signals identified at single-cell resolution generalize to an independent clinical cohort, we examined SERPINB3 expression in the METABRIC dataset comprising 2509 primary breast tumors." (PMID 41595458, 2025).
carcinoma of the larynx (2 papers, 2014 to 2018). "We also predicted that SERPINB3 was associated with uterine cancer and carcinoma of the larynx." (PMID 29949603, 2018).
cholesteatoma (2 papers, 2012 to 2015). A pathologic process characterized by the proliferation of keratinizing squamous epithelium resulting in the accumulation of keratin and cells in the middle ear and/or mastoid. "SERPINB3 is a serine protease inhibitor associated with cellular atypia, evasion of apoptosis, and cholesteatoma proliferation." (PMID 26608071, 2015). "Our identification of SERPINB3 and the three S100 proteins in cholesteatoma matrix agrees with existing literature noting increased levels in cholesteatoma relative to post-auricular skin, but it is a potentially novel finding to find increased abundance relative to middle ear mucosa." (PMID 26608071, 2015). "Real-time PCR of PI3, SPRR1B, LCN2 (lipocalin 2), MMP1, MMP9, MMP10, MMP12, SPP1, GJB2, Bcl-xl (BCL2L1), cIAP2 (BIRC3), S100A7A (koebnerisin), S100A9, SERPINB3, CEACAM6, KRT6B and SERPINB4 revealed that the expression levels of these proteins were higher in cholesteatoma than in external canal skin." (PMID 23285167, 2012).
chronic obstructive pulmonary disease (2 papers, 2022). A chronic and progressive lung disorder characterized by the loss of elasticity of the bronchial tree and the air sacs, destruction of the air sacs wall, thickening of the bronchial wall, and mucous accumulation in the bronchial tree. "SERPINB3 is upregulated in asthma patients and mediates mucus production, also in chronic obstructive pulmonary disease (COPD)." (PMID 35628512, 2022).
esophageal adenocarcinoma (2 papers, 2017 to 2024). A malignant tumor with glandular differentiation arising predominantly from Barrett mucosa in the lower third of the esophagus. "In esophageal adenocarcinoma, SerpinB3/4 expression has been associated with reduced tumor chemosensitivity as well as the impairment of immune surveillance, leading to a poor prognosis." (PMID 38201652, 2024). "Regarding SerpinB3/4 as a serological biomarker, circulating levels of the free and IgM-linked forms have also been recently investigated in the prediction of the clinical outcomes of esophageal adenocarcinoma and associated with worse overall survival." (PMID 38201652, 2024).
glioblastoma (2 papers, 2023 to 2024). The most malignant astrocytic tumor (WHO grade IV). "Among the other Serpins studied in the literature, Serpinb3 showed a suppressor of lysosomal-mediated cell death in glioblastoma cancer stem cells." (PMID 38539447, 2024).
metabolic dysfunction-associated steatohepatitis (2 papers, 2024). Metabolic dysfunction-associated steatohepatitis (MASH, formerly known as nonalcoholic steatohepatitis or NASH) is a type of fatty liver disease. "In a diet-induced non-alcoholic steatohepatitis (NASH) model, treatment with 1-PPA, a recently identified Par2 inhibitor, effectively suppressed the PAR2—C/EBP-β—SerpinB3 axis, resulting in protection against NASH development and progression." (PMID 38816842, 2024).
nasal polyp (2 papers, 2018 to 2024). "Using the Metascape platform, we matched DEGs with the target genes of diseases in the DisGeNET database and found that both DEGs of SerpinB3 and SerpinB4 were associated with nasal polyps and inflammation." (PMID 38550710, 2024). "Both the DEGs of SerpinB3 and B4 were associated with disease genes of nasal polyps and inflammation in DisGeNET database." (PMID 38550710, 2024). "We investigated SerpinB3 and B4 expression and their roles in chronic rhinosinusitis with nasal polyps (CRSwNP)." (PMID 38550710, 2024).
tongue squamous cell carcinoma (2 papers, 2020 to 2022). A squamous cell carcinoma that arises from the tongue. "The SERPINB3 promoter was more active in the TCA8113 cell line (tongue squamous cell carcinoma) than in the other cell lines." (PMID 32017381, 2020). "We used the specific regulation effect of the SERPINB3 gene on the PE38KDEL bacterial toxin, which plays a targeted toxic role in the TCA8113 cell line, to achieve gene targeting in the treatment of tongue squamous cell carcinoma." (PMID 32017381, 2020).
uterine cancer (2 papers, 2018 to 2023). Primary or metastatic malignant neoplasm involving the uterine corpus and/or the cervix. "Notably, analysis of TCGA Pan-Cancer Atlas showed a consistent positive correlation between SERPINB3 and CXCL1, CXCL8, S100A8, and S100A9 across multiple tumor types including bladder, breast, head and neck, lung, prostate, and uterine cancers." (PMID 37279067, 2023).
allergic asthma (1 paper, 2017). A asthma with a basis in a pathological type I hypersensitivity reaction. "SerpinB3 and serpinB4 were upregulated in affected skin of eczema patients and in the airway epithelia of patients with allergic asthma, induced via a pathway involving the Th2 cytokines IL-4 and IL-1347–49." (PMID 29051540, 2017).
bronchiolitis obliterans (1 paper, 2026). "Importantly, we identify SERPINB3 as a major autoantibody target with an expression pattern and clinical association suggesting a role in bronchiolitis obliterans." (PMID 41519944, 2026).
cervical disease (1 paper, 2017). "From our analysis, DSG1, KDR, and SERPINB3 expression may have potential as robust markers that can risk-stratify cervical disease, i.e., identify cervical disease cases that have a high probability of regression, and this would be of significant clinical value." (PMID 29021401, 2017). "Statistically significant changes in KDR and SERPINB3 expression, like the known biomarker KRT17, indicate their potential in identifying high-grade cervical disease." (PMID 29021401, 2017).
colorectal tumor (1 paper, 2017). "In order to further elucidate the potential involvement of SerpinB3 in colorectal tumor progression, we analyzed its expression levels in relation to disease stage." (PMID 28178650, 2017). "The absolute quantification of SerpinB3, COX-2 and β-Catenin mRNA expression, normalized by the HPRT1 housekeeping gene, was assessed in 105 primary human colorectal tumors (T) and in their corresponding adjacent non-tumor mucosa (N) by quantitative Real-Time PCR." (PMID 28178650, 2017).